GPR26 (G protein-coupled receptor 26)
Description:
Orphan receptor. Displays a significant level of constitutive activity. Its effect is mediated by G(s)-alpha protein that stimulate adenylate cyclase, resulting in an elevation of intracellular cAMP.
Tractability: Small molecule: it belongs to a druggable protein family. Antibody: UniProt places it where antibodies can reach, with medium confidence; UniProt predicts a signal peptide or a membrane-spanning region; its Gene Ontology location is reachable by antibodies, with medium confidence.
Target class: Family A G protein-coupled receptor; Membrane receptor
Gene: Protein-coding gene on chromosome 10 (123,666,355 to 123,697,399, forward strand). Ensembl gene ENSG00000154478.
Subcellular location: Cell membrane
Gene Ontology:
Molecular function: G protein-coupled receptor activity
Biological process: adenylate cyclase-activating G protein-coupled receptor signaling pathway; G protein-coupled receptor signaling pathway
Cellular component: membrane; plasma membrane
Genetic constraint (gnomAD): Loss-of-function variants: 12 observed, 14.95 expected, observed/expected ratio (o/e) 0.8, 90% interval 0.51 to 1.3. The upper end of that interval is the gene's LOEUF score, 1.3, which puts it in group 5 of 6, group 1 being the genes least tolerant of losing a copy. Missense variants: 313 observed, 367.79 expected, observed/expected ratio (o/e) 0.85, 90% interval 0.77 to 0.94. Synonymous variants: 200 observed, 172.63 expected, observed/expected ratio (o/e) 1.16, 90% interval 1.03 to 1.3.
Homologues: Orthologues: chimpanzee GPR26 (100% identical), macaque GPR26 (99% identical), dog GPR26 (98% identical), pig GPR26 (96% identical), mouse Gpr26 (95% identical), guinea pig GPR26 (93% identical), rat Gpr26 (92% identical), rabbit GPR26 (80% identical), tropical clawed frog gpr26 (64% identical), zebrafish gpr26 (63% identical). Paralogues in human: GPR78 (50% identical), GPR63 (20% identical), GPR45 (20% identical).
Diseases named in the same sentence as GPR26 in open-access papers:
GPR26 is named in the same sentence as 19 diseases in open-access papers, as found by Europe PMC text mining. Sharing a sentence is not in itself a finding about the gene and the disease. The quoted sentences say what the papers report.
Anxiety (13 papers, 2012 to 2024). Intense feelings of nervousness, tension, or panic often arise in response to interpersonal stresses. "Gpr26‐deficient mice showed heightened levels of anxiety‐like behaviour in the elevated plus maze and open field test and increased depression‐like behaviours in the Porsolt swim and tail suspension tests." (PMID 38073127, 2024). "This same study linked GPR26 to anxiety and depression, two disorders that are often co‐morbid with alcohol and other substance use disorders." (PMID 38073127, 2024). "Lphn2 has been implicated in postsynaptic target recognition in the hippocampus and Gpr26 is apparently related to anxiety and depression associated behaviors." (PMID 33996801, 2021). "In addition, according to behaviouraltests, Gpr26-deficient mice display increased anxiety- anddepression-like behavior, and prefer ethanol to a greater extentthan mice with normal genotype." (PMID 38213702, 2023). "Gpr26 deficient mice have been reported to show anxiety and depression-like behaviour." (PMID 23457544, 2013). "This hypothesis is supported by a recent report that GPR26 deficiency in mice causes increased anxiety and depression." (PMID 22815809, 2012). "Consequently, a GPR26 activator could also be used for the treatment of depression and anxiety which are often associated with an increased risk of obesity." (PMID 22815809, 2012). "Two brain-specific Gαs coupled orphan receptors that have recently been associated with anxiety- and depression-like behaviors, are GPR3 and GPR26." (PMID 33589739, 2022). "Behavioral tests on GPR26 knockout mice indicated that GPR26 is important in regulating anxiety- and depression-like behaviors." (PMID 35056845, 2022). "There are some orphan GPCRs which are highly expressed in the PFC and that have been associated with anxiety- and depression-like traits, such as GPR158, GPR56, GPR3, and GPR26." (PMID 33589739, 2022). "However, little further exploration has arisen from these studies, and no novel targeting methods have been developed to further explore the links between GPR26, anxiety, depression, and alcohol intake." (PMID 38073127, 2024). "Gpr26 KO mice also displayed reduced CREB phosphorylation in the CeA compared with WT counterparts, a process that has been linked to heightened anxiety and alcohol consumption." (PMID 38073127, 2024). "Genetic deletion of GPR26 leads to anxiety and depression-like behaviors." (PMID 37365488, 2023). "Gpr26 knockout mice show increased levels of anxiety and depression‐like behaviours [2209]." (PMID 29055040, 2017).
Obesity (6 papers, 2012 to 2024). Accumulation of substantial excess body fat. "This role seems to be attributed to GPR26, whose deficiency has been associated with obesity and diabetes, both of which are known risk factors for IS." (PMID 39650478, 2024). "Targeted inactivation of GPR26 in mice causeshyperphagia leading to early onset of diet-induced obesity." (PMID 38213702, 2023). "We show that GPR26 deficiency causes hyperphagia and hypometabolism, leading to early onset of diet-induced obesity." (PMID 22815809, 2012). "Accordingly, GPR26 deficiency also caused metabolic complications commonly associated with obesity, including glucose intolerance, hyperinsulinemia, and dyslipidemia." (PMID 22815809, 2012). "Depletion of GPR26 has been shown to increase fat storage in C. elegans, whereas GPR26 deficiency in the hypothalamus is associated with high genetic susceptibility to the onset of obesity in mice." (PMID 22815809, 2012). "To gain further insight into the molecular mechanisms underlying hyperphagia and obesity in GPR26−/− mice, we next analyzed consequence of GPR26 deficiency on AMPK signaling in the brain." (PMID 22815809, 2012). "Consistent with increased adiposity, GPR26-decificent mice also developed co-morbidities commonly associated with obesity, including hyperinsulinemia, hyperleptinemia, and dyslipidmia which are known to cause insulin resistance." (PMID 22815809, 2012). "The GPR26 mRNA is most abundantly expressed in the brain region associated with appetite control, and the human GPR26 gene has been mapped to an obesity locus on chromosome 10 q26." (PMID 22815809, 2012). "We show that mice with GPR26 deficiency exhibit hyperphagia and decreased energy expenditure, leading to high propensity to diet-induced obesity and its related metabolic complications." (PMID 22815809, 2012). "To determine a role of GPR26 in regulating obesity-related metabolic complications, we next analyzed changes in serum levels of insulin, ghrelin, adiponectin, and lipids in GPR26−/− mice on a high-fat diet." (PMID 22815809, 2012). "To determine the mechanisms by which GPR26 accelerates diet-induced obesity in GPR26−/− mice, we next analyzed changes in food intake during the 12 weeks period of feeding with a high-fat diet (HFD)." (PMID 22815809, 2012). "In the present study, we investigated a role of GPR26 in regulating the onset of diet-induced obesity and its related metabolic complications in mice with targeted deletion of the GPR26 gene." (PMID 22815809, 2012). "Our data showed that GPR26-decificent mice exhibit hyperphagia concurrently with decreased energy expenditure, leading to early onset of diet-induced obesity." (PMID 22815809, 2012). "Consistent with the findings, GPR26 deficiency significantly increased phosphorylation of AMPK at ser172, a major activation site that is implicated in hyperphgia and onset of obesity." (PMID 22815809, 2012). "Our findings identified for the first time a key role of GPR26 in energy homeostasis, suggesting that targeting GPR26 with chemical compounds may provide a novel treatment for obesity thought modulation of appetite." (PMID 22815809, 2012). "In further support of a regulatory role of GPR26 in satiety, GPR26 knockout mice also demonstrate hypersensitivity to treatment of rimonabant, an endocannabinoid receptor-1 antagonist commonly used to treat obesity by suppressing appetite in humans." (PMID 22815809, 2012). "In further support of a key role of GPR26 in regulating appetite, the GPR26 knockout mice exhibit hypersensitivity to treatment with rimonabant, an endocannabinoid receptor-1 antagonist commonly used to treat obesity by suppressing appetite in humans." (PMID 22815809, 2012). "Therefore, the results from the present studies suggest that targeting GPR26 with chemical activators may provide a novel treatment for obesity through modulation of appetite without the potential side effect of rimonabant." (PMID 22815809, 2012).
dyslipidemia (4 papers, 2012 to 2023). "Targeted deletion of Gpr26 in rodents caused glucose intolerance, hyperinsulinemia and dyslipidemia." (PMID 37895035, 2023). "In further support a role of GPR26 in metabolic complications, GPR26 also caused dyslipidemia, as evidenced by elevated levels of serum triglyceride and cholesterol in female GPR26−/− mice." (PMID 22815809, 2012). "It has been shown in animal models of metabolic syndrome that GPR26 gene-expression levels are decreased in cardiac tissues, it suggests that GPR26 could play a role in low-grade inflammation." (PMID 36362842, 2022).
Glucose intolerance (3 papers, 2012 to 2023). Glucose intolerance (GI) can be defined as dysglycemia that comprises both prediabetes and diabetes. "However, blood glucose levels in female GPR26−/− mice were significantly higher than those in the wild type control mice during oral glucose tolerance test, suggesting glucose intolerance." (PMID 22815809, 2012).
Hyperinsulinemia (3 papers, 2012 to 2023). An increased concentration of insulin in the blood. "GPR26 deficiency significantly increased serum insulin level in both female and male GPR26−/− mice, suggesting hyperinsulinemia in GPR26 knockout mice." (PMID 22815809, 2012).
diabetes (2 papers, 2022 to 2024). "To predict functional associations between orphan GPR26 and attributes, like genes and proteins associated with diabetes and related complications, we performed a bioinformatics analysis using the Harmonizome, JASPAR, KEGG, and STRING databases." (PMID 35885041, 2022). "However, data regarding the role of GPR26 in diabetes and inflammatory associated complications are missing." (PMID 35885041, 2022). "Autophagy, commonly activated in immune cells to regulate inflammation following oxidative injury in diabetes, was impaired by GPR26 knockdown." (PMID 35885041, 2022). "Moreover, analysis of GPR26 expression and function in other cell types related to diabetes and cardiovascular complications, such as endothelial cells that are closely related to immune cell activation in diabetic patients, could provide more information and better clarify the role of GPR26 in T2D." (PMID 35885041, 2022).
Hyperglycemia (2 papers, 2012 to 2022). An increased concentration of glucose in the blood. "Chronic and prolonged exposure of monocytes to hyperglycemia impaired GPR26 protective effects and lead to its internalization and ineffective activation." (PMID 35885041, 2022). "Next, we examined the role of GPR26 on hyperglycemia-mediated monocyte inflammatory activation and adhesion to HAoECs." (PMID 35885041, 2022). "Taken together, these data indicated that hyperglycemia promotes monocyte adhesion to ECs by suppressing GPR26′s anti-inflammatory role." (PMID 35885041, 2022). "Our data suggested that THP1 might initially activate a mechanism of defense in response to hyperglycemia, which is partly mediated by a positive feedback loop that involves GPR26 activation." (PMID 35885041, 2022). "Our data indicated that orphan GPR26 is downregulated in diabetic patients and might be initially activated in monocytes and PBMCs to counteract the pro-inflammatory and apoptotic activation mediated by hyperglycemia." (PMID 35885041, 2022). "Hence, inhibition of GPR26 in diabetic patients might sustain hyperglycemia-mediated NF-κB activation." (PMID 35885041, 2022). "Hence, these data supported the hypothesis that GPR26 might be activated to protect monocytes against hyperglycemia-mediated detrimental effects." (PMID 35885041, 2022). "Hence, hyperglycemia might impair GPR26 to inhibit autophagy in monocytes." (PMID 35885041, 2022). "However, GPR26 expression was initially enhanced in human monocytes (THP-1) and human PBMCs treated with HG, a surrogate of hyperglycemia, whereas it was decreased when cells were exposed to prolonged and chronic HG levels." (PMID 35885041, 2022).
Stroke (2 papers, 2023 to 2024). Sudden impairment of blood flow to a part of the brain due to occlusion or rupture of an artery to the brain. "The product of GPR26 representing the G-coupled protein receptor can be considered as a therapeutic target for stroke prevention." (PMID 39650478, 2024).
type 2 diabetes (2 papers, 2023 to 2024). "In patients with type 2 diabetes, GPR26 is down-regulated due to chronic hyperglycemic conditions and accompanied by increased production of reactive oxygen species, pro-inflammatory monocyte activation and adhesion to endothelial cells." (PMID 39650478, 2024). "In patients with type 2 diabetes GPR26 was downregulated due to chronic hyperglycemic conditions and accompanied by increased production of reactive oxygen species, pro-inflammatory monocyte activation and apoptosis." (PMID 37895035, 2023).
hearing loss (1 paper, 2025). "Mutations in some GPCR family proteins, such as GPR156 and GPR26, can cause hearing loss." (PMID 40248074, 2025).
hepatocellular carcinoma (1 paper, 2025). A malignant tumor that arises from hepatocytes. "Ubiquitin-dependent degradation regulates the constitutive activity of GPR26 has been studied in hepatocellular carcinoma." (PMID 40689396, 2025).
Insulin resistance (1 paper, 2012). Increased resistance towards insulin, that is, diminished effectiveness of insulin in reducing blood glucose levels. "Consistent with exclusive expression of GPR26 in the brain, GPR26 did not affect AMPK phosphorylation in the liver which plays an important role in suppressing hepatic gluconeogenesis and insulin resistance." (PMID 22815809, 2012).
ischemic stroke (1 paper, 2024). A stroke disorder caused by obstruction of blood flow to the brain, due to thrombotic (local blood clot formation) or embolic (due to a blood clot or other material traveling from another site) event. "The underlying mechanism of GPR26 association with ischemic stroke is to be clarified." (PMID 39650478, 2024).
GPR26 also shares sentences with these, for which no sentence is quoted: depression (10 papers); dyslexia (1); Hyperphagia (1); Impaired glucose tolerance (1); neurodegenerative disease (1); tumours (1).